BPI (bactericidal permeability increasing protein)
Description:
The cytotoxic action of BPI is limited to many species of Gram-negative bacteria; this specificity may be explained by a strong affinity of the very basic N-terminal half for the negatively charged lipopolysaccharides that are unique to the Gram-negative bacterial outer envelope. Has antibacterial activity against the Gram-negative bacterium P.aeruginosa, this activity is inhibited by LPS from P.aeruginosa.
Synonyms: BPIFD1; rBPI
Tractability: Small molecule: a structure with a bound ligand is known; it has a high-quality binding pocket. Antibody: UniProt places it where antibodies can reach, with high confidence; its Gene Ontology location is reachable by antibodies, with high confidence; UniProt predicts a signal peptide or a membrane-spanning region. PROTAC: ubiquitination databases record sites on it; its protein half-life has been measured.
Gene: Protein-coding gene on chromosome 20 (38,260,141 to 38,337,505, forward strand). Ensembl gene ENSG00000101425.
Subcellular location: Secreted; Cytoplasmic granule membrane
Pathways (Reactome):
Immune System: Antimicrobial peptides; Neutrophil degranulation; Toll Like Receptor 4 (TLR4) Cascade
Gene Ontology:
Molecular function: lipopolysaccharide binding; lipid binding
Biological process: negative regulation of interleukin-6 production; negative regulation of interleukin-8 production; negative regulation of macrophage activation; negative regulation of tumor necrosis factor production; defense response to Gram-negative bacterium; innate immune response; lipopolysaccharide-mediated signaling pathway
Cellular component: extracellular exosome; extracellular region; azurophil granule lumen; specific granule lumen
Genetic constraint (gnomAD): Loss-of-function variants: 48 observed, 60.4 expected, observed/expected ratio (o/e) 0.79, 90% interval 0.63 to 1.01. The upper end of that interval is the gene's LOEUF score, 1.01, which puts it in group 4 of 6, group 1 being the genes least tolerant of losing a copy. Missense variants: 648 observed, 636.17 expected, observed/expected ratio (o/e) 1.02, 90% interval 0.95 to 1.09. Synonymous variants: 236 observed, 249.75 expected, observed/expected ratio (o/e) 0.94, 90% interval 0.85 to 1.05.
Homologues: Orthologues: chimpanzee BPI (98% identical), macaque BPI (89% identical), dog BPI (67% identical), pig BPI (64% identical), rabbit BPI (62% identical), rat Bpi (55% identical), mouse Bpi (54% identical), tropical clawed frog bpi (48% identical), tropical clawed frog bpi.4 (42% identical). Paralogues in human: LBP (44% identical), BPIFC (28% identical), PLTP (25% identical), BPIFB6 (21% identical), CETP (20% identical), BPIFB4 (19% identical), BPIFB3 (18% identical), BPIFB2 (17% identical), BPIFB1 (13% identical), BPIFA3 (9% identical), BPIFA1 (7% identical), BPIFA2 (5% identical).
Diseases named in the same sentence as BPI in open-access papers:
BPI is named in the same sentence as 81 diseases in open-access papers, as found by Europe PMC text mining. Sharing a sentence is not in itself a finding about the gene and the disease. The quoted sentences say what the papers report.
Sepsis (18 papers, 2013 to 2025). Sepsis is defined as life-threatening organ dysfunction caused by a dysregulated host response to infection. "Since BPI polymorphism possibly influences a variety of diseases including sepsis, GvHD, and allergy, in vivo models would be of interest." (PMID 35163248, 2022). "Premature neonates heterozygous for both BPI variants had a significantly lower risk for developing sepsis compared to those homozygous for BPI216E." (PMID 35163248, 2022). "Our group focuses on the paediatric population and previously demonstrated that interleukin 6 (IL-6) and bactericidal permeability increasing protein (BPI) polymorphisms are associated with different outcomes of sepsis." (PMID 24383711, 2014). "A polymorphism in the BPI gene (Lys/Glu - 216) was reported to be associated with increased risk for development of sepsis but is uncorrelated with gender; while a corresponding genetic variation in LBP is related to male gender." (PMID 24391897, 2013). "Importantly, clinical studies have indicated an impact of the single nucleotide polymorphism (SNP) rs4358188 within the BPI gene in the context of sepsis." (PMID 35163248, 2022). "Moreover, BPI A + LBP A + TLR A +HSP70 A +IL-6 B was also a high-risk combination for sepsis (p=0.016)." (PMID 34295331, 2021). "However, whereas SNPs in the IL1β and in MMP-16 genes were associated with an increased risk of sepsis, variations of BPI and DEFβ1 seemed to play a protective role." (PMID 25000179, 2014). "Susceptibility to sepsis in our study population was related to SNPs in the IL1β, MMP-16, BPI, and DEFβ1 genes." (PMID 25000179, 2014). "A non-associated combination of wild-type homozygote variants of BPI and HSP 70 genes together represented high risk for sepsis development (P < 0.001), and this was statistically significant for PGS (P = 0.004)." (PMID 24383711, 2014). "Specific combinations of common homozygosity for BPI, LBP, TLR, HSP 70 and IL-6 variants were typical within the septic group and were associated with a high risk of sepsis development." (PMID 24383711, 2014). "Peripheral blood transcriptomics in humans have shown a parallel scenario since particular key mediators of the initial neutrophil response to infection, such as LCN2, BPI, CD24, CASP1 and MMP8, were strongly dysregulated in patients with sepsis-associated ARDS compared to sepsis patients." (PMID 31426444, 2019). "HNP 1–3, lactoferrin, BPI, and heparin-binding protein are increased in sepsis." (PMID 26347737, 2015). "Bactericidal/permeability-increasing protein (BPI) is relevant in preventing disease and sepsis in neonates." (PMID 39858883, 2025). "Furthermore, it was shown that HNP 1–3, lactoferrin, BPI, and heparin-binding protein (HBP) exerted higher levels in neonates with sepsis." (PMID 26347737, 2015). "Recombinant N-terminal fragments of BPI (including rBPI23 and rBPI21 [opebacan, NEUPREX®]) possessing the LPS-binding and LPS-neutralizing activity of native BPI were developed by XOMA (US) LLC (Berkeley, CA) as anti-infective agents for use in sepsis and other infectious disease indications." (PMID 26835003, 2015).
cystic fibrosis (9 papers, 2015 to 2025). Autosomal recessive disorder caused by pathogenic variants in the CFTR gene (cystic fibrosis transmembrane conductance regulator), which encodes a chloride and bicarbonate channel expressed in epithelial cells, and follow the diagnosis criteria. "Anti-BPI antibodies are frequently detected in patients with cystic fibrosis and Pseudomonas infections." (PMID 40453087, 2025). "Unfortunately, many people with cystic fibrosis also generate antibodies that bind to BPI and interfere with its antimicrobial function." (PMID 37461324, 2023). "BPI-mediated killing of E. coli was impaired by anti-BPI antibodies from pediatric cystic fibrosis patients, and neutrophil-mediated killing of E. coli was inhibited by the addition of neutralizing anti-BPI serum from rabbit." (PMID 32747603, 2020). "Although not previously connected to RA, several of these genes were recently shown to be implicated in autoimmunity (e.g. CARD6 in psoriasis, PTGDR in asthma, BPI in cystic fibrosis) and immune-related processes." (PMID 28148290, 2017). "Antibody autoreactivity against bactericidal/permeability-increasing protein (BPI) is strongly associated with Pseudomonas aeruginosa infection in cystic fibrosis, non-CF bronchiectasis (BE), and chronic obstructive pulmonary disease (COPD)." (PMID 32747603, 2020). "Bactericidal/permeability-increasing protein-anti-neutrophil cytoplasmic antibodies (BPI-ANCA) from people with cystic fibrosis (PwCF) do not recognize orthologous proteins of human BPI (huBPI)." (PMID 37461324, 2023). "Additionally, we found that anti-BPI IgG in bacteremia, bronchiectasis, and cystic fibrosis patients were all of the IgG1, not the IgG2, subclass." (PMID 32747603, 2020).
inflammatory bowel disease (6 papers, 2012 to 2025). A spectrum of small and large bowel inflammatory diseases of unknown etiology. "In inflammatory bowel disease and Wegener's granulomatosis patients, anti-BPI antibodies were shown to impair the antibiotic activity of BPI protein." (PMID 32747603, 2020). "One study found BPI is a significant minority target antigen for ANCAs in inflammatory bowel disease that seems related to colonic Crohn’s disease and disease activity in ulcerative colitis." (PMID 32565845, 2020). "Anti-BPI autoantibody levels are increased in patients with inflammatory diseases (such as systemic sclerosis and inflammatory bowel disease), whereas systemic sclerosis patients with high anti-BPI antibody levels show decreased skin inflammation in the absence of renal involvement." (PMID 34815797, 2021). "Anti-neutrophil cytoplasmic antibodies (ANCA) with BPI specificity have been identified in different diseases associated with Gram-negative bacteria, such as inflammatory bowel diseases (IBD) and primary sclerosing cholangitis, and are frequently present in CF patients." (PMID 23346184, 2012).
bronchiectasis (5 papers, 2018 to 2025). Segmental, irreversible dilation of the bronchial tree resulting in the accumulation of secretions which leads to obstruction. "Anti-BPI autoantibodies strongly associate with severity of disease, including poor lung function in CF, bronchiectasis, and COPD." (PMID 34142075, 2021). "Bronchiectasis patients exhibited markedly higher anti-BPI avidity than patients with bacteremia." (PMID 32747603, 2020). "Anti-BPI antibodies in bacteremic patients (acute infections) were of low-avidity, compared to those in CF or bronchiectasis (chronic infections) patients, suggesting the breaking of tolerance to BPI arises through affinity maturation rather than cross-reactivity to P. aeruginosa." (PMID 34142075, 2021).
influenza (5 papers, 2016 to 2024). An acute viral infection of the respiratory tract, occurring in isolated cases, in epidemics, or in pandemics; it is caused by serologically different strains of viruses (influenzaviruses) designated A, B, and C, has a 3-day incubation period, and usually lasts for 3 to 10 days. "BPI, an antimicrobial gene with a known role in innate immunity and which can inhibit the infectivity of influenza, was also found to be differentially expressed only in pigeon and goose." (PMID 36926515, 2023). "The concentrations of the RETN, MMP8, LCN2, ELANE and BPI in plasma tended to be higher in influenza patients than healthy donors." (PMID 33448094, 2021). "A 27 aa peptide from the N-terminal part of human bactericidal/permeability-increasing protein (BPI) previously shown to harbour antibacterial activity inhibits the infectivity of multiple Influenza A virus strains (H1N1, H3N2 and H5N1) the causing agent of the Influenza pneumonia." (PMID 27273104, 2016). "Area under the curve (AUC) analysis of ROC showed that LCN2, BPI, ELANE and MMP8 expression represented severe influenza infection." (PMID 33448094, 2021). "Among them, some proteins related to specific neutrophils granules, such as bactericidal/permeability‐increasing (BPI) protein and matrix metalloproteinase‐8 (MMP8) protein, were generally more abundant in relative severe influenza cases." (PMID 33448094, 2021).
vasculitis (5 papers, 2013 to 2025). "Other ANCAs have also been described, including those against α-enolase, bactericidal permeability-increasing protein (BPI), cathepsin G, elastase, and lactoferrin, but they are rarely associated with vasculitis." (PMID 38673537, 2024). "Thus, anti-BPI ANCA positivity in pwCF (or other conditions such as primary vasculitis) may contribute to bacterial colonization and/or susceptibility to infection." (PMID 33282799, 2020). "Whether anti-BPI ANCA is involved in the pathogenesis of vasculitis has not been clarified." (PMID 24959541, 2013).
Arthritis (3 papers, 2020 to 2023). Inflammation of a joint. "We compared BPI autoreactivity in patients with S. aureus bacteremia with that in patients with S. aureus arthritis and osteomyelitis." (PMID 32747603, 2020). "BPI overexpression in T-cell-derived exosomes or peripheral blood T cells may be a biomarker and pathogenic factor for human SLE nephritis, hepatitis, and arthritis." (PMID 34815797, 2021). "Among them, AREG, BPI and TAP1 genes showed an increased expression in arthritis participants." (PMID 38022684, 2023). "Taken together, BPI overexpression in T cells and T-cell-derived exosomes may be a potential biomarker for SLE arthritis, hepatitis, and nephritis." (PMID 34815797, 2021).
asthma (3 papers, 2017 to 2022). "Three other antimicrobial protein families have been investigated in asthma, namely bactericidal/permeability-increasing protein (BPI), the palate, lung and nasal epithelium clone PLUNC family and defensins, yet their potential influence in allergic rhinitis remains to be determined." (PMID 32266843, 2020).
systemic lupus erythematosus (3 papers, 2021 to 2025). An autoimmune multi-organ disease typically associated with vasculopathy and autoantibody production. "Autoantibodies identified in this study included anti-C1q antibodies, previously observed in systemic lupus erythematosus, as well as anti-β2GP1, anti-bactericidal/permeability-increasing protein (BPI), and anti-ACE-2 antibodies." (PMID 40313948, 2025). "Some of the autoantibodies discovered included anti-C1q antibodies, also seen in systemic lupus erythematosus, anti-β2GP1 antibodies, anti-bactericidal/permeability-increasing protein (BPI) antibodies, and anti-ACE-2 antibodies." (PMID 36937488, 2023).
viral infection (3 papers, 2016 to 2022). "Increased expression of BPI and PLSCR2 has also been associated with the immune response of cows to bacterial and virus infection, respectively." (PMID 32792605, 2020). "Several genes in this group (CTSG, encoding the neutrophil serin protease Cathepsin G; DEAFA4, defensin alpha 4; LCN2, lipocalin 2; OLFM4, BPI and CD24), are known to be overexpressed in patients with severe viral infections, including COVID-197,14." (PMID 35181735, 2022). "However, unlike known BPI, rCsBPI exhibits novel properties unreported previously, i.e. immunoregulatory effect and the ability to inhibit not only bacterial but also viral infection in vivo, though the effect on virus is likely an indirect one mediated by rCsBPI-induced antiviral immune response." (PMID 27105425, 2016).
Autoimmunity (2 papers, 2017 to 2021). The occurrence of an immune reaction against the organism's own cells or tissues. "Understanding this role takes on particular interest with the recognition that autoimmunity to BPI is tightly linked to a specific infectious trigger like Pseudomonas aeruginosa in chronic lung infection." (PMID 34142075, 2021).
bacteremia (2 papers, 2020 to 2021). "P. aeruginosa was an infrequent cause of bacteremia in this cohort; hence, sera from patients with P. aeruginosa were uncommon (12/154), with 33.3% (4/12) exhibiting anti-BPI antibodies." (PMID 32747603, 2020). "Tracking a subset of the DHMC bacteremia cohort over time revealed that anti-BPI autoantibody titers significantly decreased with time." (PMID 32747603, 2020). "We examined the pathogen-specific nature of this autoreactivity by examining antibodies to BPI in bacteremia patients." (PMID 32747603, 2020). "The rapid induction of anti-BPI IgG with bacteremia suggests that T cell-dependent follicular maturation of IgG-bearing B cells characterized by affinity maturation was unlikely." (PMID 32747603, 2020). "The evidence of decreased BPI autoreactivity titers over time, together with the low anti-BPI IgG avidity shown in the bacteremia cohort, suggests that BPI autoreactivity arises in a T cell-independent manner without follicle-dependent B cell maturation." (PMID 32747603, 2020). "Slightly lower mean titers of IgG anti-BPI antibodies were seen in GNB bacteremia than in bacteremia from Gram-positive bacteria (GPB) (mean number of AU, 87 versus 127, respectively)." (PMID 32747603, 2020). "The strong relationship between BPI antibody autoreactivity and bacteremia was observed in a retrospective cohort restricted to GNB." (PMID 32747603, 2020). "This notion was supported by the demonstration that anti-BPI antibody responses in bacteremia were of low avidity, in contrast to those seen in CF and BE." (PMID 32747603, 2020). "In the DHMC bacteremia cohort, 43.5% of anti-BPI IgG-positive patients (n = 23) were positive within the first 5 days of testing positive for infection, suggesting that anti-BPI antibody was induced early during the course of infection." (PMID 32747603, 2020). "We report higher BPI protein levels in bacteremia patients than in healthy controls." (PMID 32747603, 2020). "Anti-BPI autoantibodies were found in 2/15 (13.3%) patients with chronic S. aureus infection (S. aureus [URMC]), approximating the rate seen in acute S. aureus bacteremia (S. aureus [DHMC])." (PMID 32747603, 2020). "Interestingly, we show that autoantibodies to neutrophil antigens other than BPI, such as PR3, may arise in bacteremia." (PMID 32747603, 2020).
chronic lung infection (2 papers, 2021). "While autoantibodies to BPI are found in other disease states, high-avidity autoantibodies are restricted to patients with chronic lung infection with P. aeruginosa." (PMID 33981306, 2021).
colonic Crohn’s disease (2 papers, 2020 to 2025). "Among the studies carried out, a reduction in mortality in children with meningococcal sepsis (clinical phases II and III) and beneficial effects in patients with Crohn’s disease (clinical phase II) stand out in both cases when treated with an N-terminal fragment of recombinant BPI (rBPI21)." (PMID 39858883, 2025).
COVID-19 (2 papers, 2023 to 2025). A disease caused by infection with severe acute respiratory syndrome coronavirus 2. "We found that PDE5A, ITGB3, CEACAM8, and BPI were hub-shared genes in IS and COVID-19, which were remarkably enriched in pathways such as ECM-receptor interaction and focal adhesion pathways." (PMID 37090981, 2023).
gram-negative bacterial infections (2 papers, 2016 to 2024). Infections caused by bacteria that show up as pink (negative) when treated by the gram-staining method. "Thus, BPI is an attractive target in the management of both infections and inflammatory diseases, and recombinant BPI and its derivatives have shown promise in the treatment of gram-negative bacterial infections in preclinical as well as clinical trials." (PMID 27338589, 2016). "BPI may interact directly with the mycobacterial surface to limit the cytokine production that follows the recognition of mycobacteria, thus inducing an anti-inflammatory effect, as reported for Gram-negative bacterial infections." (PMID 38672491, 2024).
meningococcal disease (2 papers, 2018 to 2022). "Lethality in this patient group during the course of Gram-negative sepsis is high and the application of a recombinant N-terminal domain of BPI showed partial clinical success in children with meningococcal infection." (PMID 35163248, 2022).
Obesity (2 papers, 2018 to 2024). Accumulation of substantial excess body fat. "In the process of integrating multi-omics correlation analysis, we identified a set of biomarkers with well-interconnected networks implicated in obesity, such as BPIFA1, BPI, SAA1, PDE1C, Deoxycholic acid, Phthalic anhydride, DL-Alanine, p_Firmicutes, g_Intestinimonas, and g_Turicibacter." (PMID 39609876, 2024).
tuberculosis (2 papers, 2025). A chronic, recurrent infection caused by the bacterium Mycobacterium tuberculosis. "However, little is known about the role of BPI protein in Gram-positive (GP) bacterial infections and tuberculosis." (PMID 41008681, 2025). "Gaining insights into how different bacterial lysates induce macrophage activation, cytokine production, and the expression of antimicrobial effectors, such as BPI, which can decrease intracellular bacterial growth, may reveal new strategies for host-directed therapy (HDT) in tuberculosis (TB)." (PMID 41154675, 2025).